CACNG4 (calcium voltage-gated channel auxiliary subunit gamma 4)
Description:
Regulates the activity of L-type calcium channels that contain CACNA1C as pore-forming subunit. Regulates the trafficking and gating properties of AMPA-selective glutamate receptors (AMPARs), including GRIA1 and GRIA4. Promotes their targeting to the cell membrane and synapses and modulates their gating properties by slowing their rates of activation, deactivation and desensitization and by mediating their resensitization.
Synonyms: MGC11138; MGC24983
Tractability: Small molecule: an approved drug acts on it; a high-quality ligand is known; it belongs to a druggable protein family. Antibody: UniProt places it where antibodies can reach, with high confidence; its Gene Ontology location is reachable by antibodies, with high confidence; UniProt predicts a signal peptide or a membrane-spanning region.
Gene: Protein-coding gene on chromosome 17 (66,964,707 to 67,033,400, forward strand). Ensembl gene ENSG00000075461.
Subcellular location: Cell membrane
Subcellular location (Human Protein Atlas): Vesicles
Pathways (Reactome):
Muscle contraction: Phase 0 - rapid depolarisation; Phase 2 - plateau phase
Neuronal System: Presynaptic depolarization and calcium channel opening; Trafficking of AMPA receptors
Developmental Biology: LGI-ADAM interactions
Gene Ontology:
Molecular function: calcium channel regulator activity; protein binding; channel regulator activity; voltage-gated calcium channel activity; ionotropic glutamate receptor binding
Biological process: regulation of AMPA receptor activity; positive regulation of synaptic transmission, glutamatergic; postsynaptic neurotransmitter receptor diffusion trapping; transmission of nerve impulse; calcium ion transmembrane transport; calcium ion transport; positive regulation of insulin secretion involved in cellular response to glucose stimulus; response to cocaine
Cellular component: L-type voltage-gated calcium channel complex; AMPA glutamate receptor complex; endocytic vesicle membrane; plasma membrane; postsynaptic density membrane; cell body; cell surface; glutamatergic synapse; membrane; somatodendritic compartment; voltage-gated calcium channel complex
Genetic constraint (gnomAD): Loss-of-function variants: 7 observed, 22.27 expected, observed/expected ratio (o/e) 0.31, 90% interval 0.18 to 0.59. The upper end of that interval is the gene's LOEUF score, 0.59, which puts it in group 2 of 6, group 1 being the genes least tolerant of losing a copy. Missense variants: 357 observed, 450.7 expected, observed/expected ratio (o/e) 0.79, 90% interval 0.73 to 0.87. Synonymous variants: 188 observed, 188.51 expected, observed/expected ratio (o/e) 1, 90% interval 0.88 to 1.12.
Homologues: Orthologues: chimpanzee CACNG4 (100% identical), macaque CACNG4 (99% identical), mouse Cacng4 (98% identical), rat Cacng4 (98% identical), dog CACNG4 (98% identical), pig CACNG4 (97% identical), guinea pig CACNG4 (96% identical), tropical clawed frog cacng4 (81% identical), rabbit CACNG4 (78% identical), zebrafish cacng4b (74% identical), zebrafish cacng4a (59% identical), Caenorhabditis elegans stg-2 (22% identical). Paralogues in human: CACNG8 (61% identical), CACNG2 (59% identical), CACNG3 (57% identical), CACNG5 (26% identical), CACNG7 (26% identical).
Diseases named in the same sentence as CACNG4 in open-access papers:
CACNG4 is named in the same sentence as 18 diseases in open-access papers, as found by Europe PMC text mining. Sharing a sentence is not in itself a finding about the gene and the disease. The quoted sentences say what the papers report.
breast carcinoma (4 papers, 2021 to 2024). "In breast cancer, CACNG4 is upregulated in lymph node metastasis and associated with poor prognosis." (PMID 36038558, 2022). "As CACNG4 is located on the plasma membrane, antibody-based therapies have the potential to inhibit its function and impede breast cancer progression, providing a viable and valuable approach for the development of novel treatment strategies." (PMID 38291367, 2024). "The identification of CACNG4 as a potential breast cancer biomarker is an important step towards improving clinical outcomes for breast cancer patients." (PMID 38291367, 2024). "Analysis of CACNG4 mRNA expression unveiled a significant upregulation in patients with grade III breast cancer compared to patients with grade I and II tumors." (PMID 38291367, 2024). "Amplification of CACNG4 has been shown to contribute to increased breast cancer cell motility, transformation, and metastasis, highlighting the importance of targeted therapies that can disrupt its actions." (PMID 38291367, 2024). "Furthermore, the COSMIC database analyzed the mutations of the CACNG4, PKMYT1, EPYC, and CHRNA6 genes in breast cancer." (PMID 38291367, 2024). "Through bioinformatics analysis and qRT-PCR validation, we confirmed the upregulation of CACNG4, PKMYT1, EPYC, and CHRNA6 in breast cancer." (PMID 38291367, 2024). "We propose that CACNG4, PKMYT1, and CHRNA6 hold promise as potential targets for both the diagnosis and treatment of breast cancer, while EPYC has the potential to be used only as an effective diagnostic biomarker." (PMID 38291367, 2024). "Based on METABRIC database, CACNG4, PKMYT1, and CHRNA6 exhibited differential expression in breast cancer tissues compared to normal tissues." (PMID 38291367, 2024). "In another study, knockdown of the VGCC auxiliary subunit gamma 4 (CACNG4) in breast cancer cell lines reduced cell migration preferentially in the more aggressive MDA-MB-231 cells as compared to MCF7; and CACNG4 overexpression resulted in enhanced lung metastasis and death." (PMID 34069353, 2021). "Based on qRT-PCR analysis conducted on 55 breast cancer patients and normal cases, it was observed that CACNG4, PKMYT1, EPYC, and CHRNA6 mRNA exhibited significantly higher expression levels in breast cancer tissues (BCT) compared to non-tumoral adjacent tissues (NTAT) (P < 0.0001)." (PMID 38291367, 2024).
schizophrenia (4 papers, 2016 to 2024). A major psychotic disorder characterized by abnormalities in the perception or expression of reality. "Of note, the current microarray data identified four gamma subunits of the L-type voltage-gated calcium channels to be down-regulated in PCP-SI rats, and single nucleotide polymorphisms in two of these (CACNG4 and CACNG6) have recently also been associated with schizophrenia." (PMID 27382048, 2016).
Breast tumors (2 papers, 2021 to 2024). "Breast tumors with nodal metastases are also associated with higher protein expression of CACNG4 in clinical samples." (PMID 34557425, 2021). "Paired t-tests comparing the gene expression profiles of CACNG4, PKMYT1, EPYC, and CHRNA6 between breast tumors and normal tissues revealed an almost 5.55-fold, 2.31-fold, 2.32-fold, and 2.14-fold increase in breast tumors, compared to normal tissues, respectively." (PMID 38291367, 2024).
colon cancer (2 papers, 2021 to 2022). "One gene expression analysis revealed upregulation of the CACNG4 gene in human colon cancer." (PMID 34557425, 2021). "GGH, CACNG4, MME, SLC30A2, CKMT2, SYN3, and SLC22A31 were identified as differentially expressed both in glycolytic-cholesterogenic subgroups as well as between colon cancers and healthy samples, and were involved in glycolysis‒cholesterol synthesis." (PMID 36569910, 2022).
atrial fibrillation (1 paper, 2025). A disorder characterized by an electrocardiographic finding of a supraventricular arrhythmia characterized by the replacement of consistent P waves by rapid oscillations or fibrillatory waves that vary in size, shape and timing and are accompanied by an irregular ventricular response. "At the RNA level, RT-qPCR confirmed expression changes in CACNG4 (cardiac arrythmia), GJA5 (atrial fibrillation), THBS2 (angiogenesis inhibitor), ADD2 (membrane skeletal protein, synaptic plasticity), and HAND2 (neurogenesis)." (PMID 39508990, 2025).
bipolar disorder (1 paper, 2024). A disorder of the brain that causes unusual shifts in mood, energy, activity levels and the ability to carry out day-to-day tasks. "Another example is CACNB3 and CACNG4, calcium channel genes that have been associated with bipolar disorder and major depression(." (PMID 38464225, 2024).
cervical cancer (1 paper, 2021). A primary or metastatic malignant neoplasm involving the cervix. "A comparison of CACNG4 expression between tumor samples and normal tissue samples taken from TCGA and the GTEx databases showed that CACNG4 is upregulated in cervical cancer." (PMID 34557425, 2021). "Taken together, these data suggest that CACNG4 may act as a potential biomarker for the early diagnosis of cervical cancer, as well as a target for modulating intracellular calcium homeostasis, which sustains tumor growth." (PMID 34557425, 2021).
cervical disease (1 paper, 2021). "As such, CACNG4 may serve as a potential predictor for tumorigenesis in cervical disease." (PMID 34557425, 2021).
hepatocellular carcinoma (1 paper, 2025). A malignant tumor that arises from hepatocytes. "In hepatocellular carcinoma CSCs, the VGCC subunit CACNG4 is implicated in maintaining stemness, and its inhibition by amlodipine suppresses CSC characteristics." (PMID 40806720, 2025).
cancer (8 papers, 2016 to 2025). A tumor composed of atypical neoplastic, often pleomorphic cells that invade other tissues. "In particular, several differentially expressed genes (DEGs) are closely associated with cancer, such as CACNG4, which was confirmed to be upregulated at both the mRNA and protein levels." (PMID 34557425, 2021). "Next, we examined the levels of CACNG4 mRNA transcripts within cancer samples using the GEPIA2 website." (PMID 34557425, 2021). "CACNG4, an L-type voltage-gated calcium channel gamma subunit, has been reported to be overexpressed in several cancers and may promote calcium homeostasis to increase the survival and metastatic ability of tumor cells." (PMID 34557425, 2021). "The gene that was most upregulated in carcinomas was CACNG4 (FC 3.30)." (PMID 29636593, 2018). "Similarly, both CACNG4 and SCN1B are upregulated in cancer tissue and their gene products have been assigned a role in cancer progression." (PMID 32764426, 2020). "Furthermore, the most diversely expressed genes were particularly enriched in MAPK signaling pathway, such as CACNG4, CACNA1E and CACNA1H, which involve in cancer evolution and heterogeneity formation." (PMID 27602771, 2016). "Cancer and organismal injuries were the top two diseases and function categories that were predicted to increase, along with neurological (HAND2), hepatic system (APOE, CACNG4, CAMK2B), respiratory system (WNT16), and skeletal muscle developmental disorders (ADD2, HAND2)." (PMID 39508990, 2025).
tumor (3 papers, 2021 to 2024). "Mechanistically, CACNG4 affects calcium influx by modulating VGCCs, which in turn regulate the homeostasis and metastasis of tumor cells." (PMID 34557425, 2021). "Furthermore, we examined the promoter accessibility of those markers and we observed that the promoter region of CACNG4 is more open in luminal tumor and LM cells." (PMID 39478117, 2024).
infection (1 paper, 2024). The state of being infected such as from the introduction of a foreign agent such as serum, vaccine, antigenic substance or organism. "A number of pathways related to cardiac myopathy were also inhibited by inulin in both infection models, as a consequence of the suppression of many genes encoding voltage-dependent calcium channels (e.g., Cacng4) and cAMP formation (e.g., Adcy3)." (PMID 38179939, 2024).
CACNG4 also shares sentences with these, for which no sentence is quoted: Anxiety (1 paper); cardiac hypertrophy (1); dilated cardiomyopathy (1); epilepsy (1); lymph node metastasis (1); major depression (1).